ANXA1 (annexin A1)
Diseases named in the same sentence as ANXA1 in open-access papers (continued):
Sharing a sentence is not in itself a finding about the gene and the disease.
tumor (continued). "Moreover, the impairment of DCs activation, influenced by ANXA1 signaling, can suppress CD8+T cells recruitment, thereby enabling tumor progression." (PMID 41283264, 2025). "Mechanistically, ANXA1 promotes the binding of USP5 to GOT1, thus preventing the degradation of GOT1 via the ubiquitin-proteasome pathway and promoting glutamine metabolism to enhance the oxidative stress adaptation of tumor cells and promote tumor growth." (PMID 40390008, 2025). "Immunostaining on tumor samples revealed ANXA1 protein expression in tumor cells and TAMs but not on CAFs or lymphocytes." (PMID 40361334, 2025). "Next, we further explored whether ANXA1 could affect GOT1-mediated glutamine metabolism and its mechanism of promoting tumor cell proliferation." (PMID 40390008, 2025). "In ANXA1-knockdown cells, the levels of aspartat and glutamate were significantly reduced compared to controls, overexpression of GOT1 in ANXA1 knockdown cells reversed the stabilizing effect of ANXA1 knockdown on GOT1, a trend also observed in the xenograft tumor model." (PMID 40390008, 2025). "Regardless of the absence of vascular anomalies, ANXA1 lacks the ability to impair tumor-induced neovascularization, leading to tumor growth and metastasis suppression in ANXA1-knockout mice." (PMID 41283264, 2025). "Taken together, the number of tumor-infiltrating CD8+ T cells was positively correlated with the density of DCs, indicating that ANXA1-induced DC dysfunction and subsequent decrease in DC numbers may impede the anti-tumor immune response." (PMID 40484878, 2025). "Additionally, under hypoxic stress, ANXA1 inhibits glycolytic reprogramming mediated by HIF-1α, thereby reducing the sensitivity of tumor cells to rituximab." (PMID 41189944, 2025). "While ANXA1 was enriched in MVP, pseudopalisading regions, and more diffusely infiltrative GBM peripheries, ANXA2 was elevated in TCs and ECs in comparison to lower-grade tumor samples." (PMID 41366031, 2025). "ANXA1 may also modulate the CSC population by supporting their maintenance and self-renewal capacities, contributing to tumor recurrence and reduced therapeutic efficacy." (PMID 41283264, 2025). "ANXA1 is highly expressed in patients with ICC, where it promotes tumor proliferation." (PMID 40390008, 2025). "Considering that CD44 and TNFRSF1A primarily function as receptors, while ANXA1 can participate in regulating the tumor immune microenvironment as a secreted protein, we focused on whether NRF2 regulates the tumor immune microenvironment through ANXA1." (PMID 40583858, 2025). "We propose that the extended survival observed in mice grafted with ANXA1-KO cells is attributable to the absence of tumor bulk growth and perivascular invasion and the subsequent shift towards diffuse invasion." (PMID 40683881, 2025). "On the other hand, a decrease in eigenvector centrality indicates that a gene is connected to less influential or weakening genes, possibly resulting in lower relative influence scores or reduced significance in the network, such as ANXA1, GNB3, POMC, GPER1, and TIMP1 in tumor samples." (PMID 40626556, 2025). "Moreover, knockdown of ANXA1 combined with glutamine uptake inhibition significantly suppressed ICC cell proliferation and Inhibited subcutaneous tumor formation and growth." (PMID 40390008, 2025). "Enteric glial cells had fewer potential crosstalk genes, with top regulatory factors ANXA1, TIMP1, and HLA-A, and target genes such as COL1A1 and COL3A1, which may support tumor structure and growth." (PMID 40145096, 2025). "Although the comprehensive molecular mechanisms underlying TLC388-inducd antitumor immunity remain undetermined, we proposed that TLC388 promotes DC maturation by enhancing tumor antigen presentation through STING signaling and inducing immunogenic cell death such as HMGB1, ANXA1 and CRT." (PMID 38564022, 2024).
tumor (continued). "Based on the novel mechanism of ablation of the Notch1‐p15‐mediated tumor suppression in AML hyperproliferation, targeting ANXA1 provides an effective approach for AML treatment, in which antagonizing ANXA1 using NICD inhibitory peptides is an effective strategy for AML treatment." (PMID 39447086, 2024). "In conclusion this study provides evidence validating the idea that ANXA1-targeted therapy with MDX-124 could provide a novel and effective treatment option for patients whose tumours overexpress ANXA1." (PMID 38200229, 2024). "F. nucleatum did not induce Annexin A1 in non-cancerous SB cells but Annexin A1 induced only in the tumor mass's outer layer, indicating that the induction was limited to the malignant cells." (PMID 39607612, 2024). "Studies show that when ANXA1 is absent, tumor growth is slower, it forms fewer blood vessels, and its metastatic potential is lower." (PMID 38892394, 2024). "We identified 51 upregulated genes in the tumor samples derived from the patients with relapse within 60 months, participating primarily in inflammation and innate immune responses (e.g., LYN, LY96, ANXA1)." (PMID 38256136, 2024). "Furthermore, endogenous ANXA1 promoted the proliferation of AML cells in vitro and in vivo through the ablation of Notch1‐p15‐mediated tumor suppression." (PMID 39447086, 2024). "Neither anthracycline nor oxaliplatin showed therapeutic effects in tumor cells lacking ANXA1 or immune cells lacking FPR1." (PMID 37705051, 2023). "Additionally, CXCL13+ TH1-like cells (T05) were also enriched in tumor sites, whereas CD4+ANXA1+ TCM (T02) and CX3CR1+ Teff cells (T04 and T09) were mainly detected in blood and ascites." (PMID 37488416, 2023). "Indeed, annexin A1 has been identified as an endogenous inflammatory factor that alters the TME and tumor immune response." (PMID 37056569, 2023). "Authors postulated that differential expression of Annexin-A1, as a function of HPV status, may reflect attempts to regulate expression of pro-inflammatory cytokines (e.g., IL-6) in tumor cells." (PMID 37954869, 2023). "Also, dying tumor cells release a number of nuclear and cytoplasmic proteins like high mobility group box 1 (HMGB1) and annexin A1 (ANXA1)." (PMID 36003765, 2022). "The absence of calreticulin or ANXA1, for example, is known to severely limit immune responses against tumor cells." (PMID 36015189, 2022). "Studies have found that TNBC patients with ANXA1-positive tumour cells had significantly worse overall survival compared with those who were ANXA1-negative." (PMID 36678741, 2022). "We did not determine if this Annexin was lipid/membrane bound or indeed soluble and conclude that secretion of Annexin A1 is not a general characteristic of apoptotic tumour cell death under our experimental conditions." (PMID 36123610, 2022). "Gene levels corresponding to invasion-related EV proteins showed that five genes (annexin A1, actin-related protein 3, integrin-β1, insulin-like growth factor 2 receptor and programmed cell death 6-interacting protein) were significantly higher in GBM tumours." (PMID 36071478, 2022). "Similar to ANXA1, ANXA2 may elicit either tumor-promoting or -suppressive mechanisms depending on the cancer type; however, ANXA2 is frequently enhanced in metastatic cancers." (PMID 36247003, 2022). "We inferred that ANXA1 is a potential biomarker and a candidate therapeutic target for GBM treatment and may mediate tumour immune escape through NF‐kB (p65) activation and IL‐8 upregulation." (PMID 35770335, 2022). "Two genes, ANXA1 and AKAP12, were enriched in both mouse and human TROP2-producing tumor cells." (PMID 36077674, 2022). "These previously reported roles of ANXA1 complement our findings and supports the contribution of ANXA1 to the development of cisplatin resistance irrespective of the tumours’ tissues of origin." (PMID 35084545, 2022).
tumor (continued). "In spite of its inherent roles in stimulating chemotaxis in immune cells and its pro-resolving properties, the implication of ANXA1 in secondary tumor microenvironment has not been rigorously investigated." (PMID 35382852, 2022). "In summary, we found that ANXA1 is highly expressed in M2 macrophages and MES tumor cells." (PMID 34912807, 2021). "Furthermore, we identified potential molecular targets based on our expression data in NE-low and immune-oasis tumor subsets, including CD70, ANXA1, ITGB6, TP63, IFI27, YBX3 and CXCR2." (PMID 34200100, 2021). "In support of this model, anticancer immunity after chemotherapy with anthracyclines was compromised in mice with tumours lacking AnxA1, or when the dendritic host cells lacked FPR1." (PMID 33810523, 2021). "Model mice null for annexin A1 (Anxa1) show significantly suppressed tumor growth due to lack of angiogenesis, suggesting that Anxa1 is essential for tumor vascularization." (PMID 33446132, 2021). "Annexin A1 function was investigated through stable shRNA-mediated knockdown in multiple human and mouse TNBC cell lines and by characterization of both primary tumor growth and spontaneous metastasis in immuno-compromised and immuno-competent mice." (PMID 33800279, 2021). "Interestingly, we found that epithelial-mesenchymal transition, a crucial biological process during tumor metastasis, was enriched in PTC samples with ANXA1 high expression." (PMID 33531975, 2021). "ANXA1 plays a key factor in M2 macrophages and MES tumor cells." (PMID 34912807, 2021). "Lung tumor specimens evaluated with this antibody revealed vascular (endothelial) anxA1 expression in five of eight tumor samples studied, but no vascular anxA1 expression was observed in normal lung tissue." (PMID 32497150, 2020). "In PC, the protein Annexin A1 (ANXA1) appears to be overexpressed and may be identified as an oncogenic factor, also because it is a component in tumor-deriving extracellular vesicles (EVs)." (PMID 33353163, 2020). "HER-2+ (non-luminal) tumours displayed higher ANXA1 expression than luminal B-like (HER-2+) tumours." (PMID 33276477, 2020). "Although ARID1A expression did not associate with BrC molecular subtype, HER-2+ (non-luminal) tumours depict higher ANXA1 protein levels (p < 0.001) than luminal B-like (HER-2+) tumours." (PMID 33276477, 2020). "In order to investigate the role of ANXA1 on EVs-dependent metastatic potential of PC cells, we studied the paracrine effects of EVs derived by WT and ANXA1 KO MIA PaCa-2 cells on BJ fibroblasts, one of the cellular components of the tumor microenvironment." (PMID 33353163, 2020). "Annexin A1 (anxA1) is an immunomodulatory protein that has been proposed as a tumor vascular target for antitumor biologic agents, yet to date the vascular expression of anxA1 in specific tumor indications has not been systematically assessed." (PMID 32497150, 2020). "Interestingly, recent studies indicate that the PS-binding protein annexin A1 (ANXA1) is also released during ICD and has a critical role in establishing anti-tumor immunity." (PMID 33003477, 2020). "In the B16-F10-Luc2 lung metastatic model, which was shown by IHC to express anxA1 in the tumor neovasculature, anti-anxA1 antibodies 1 and 84 did not demonstrate significant tumor uptake upon systemic injection." (PMID 32497150, 2020). "Moreover, knockout of either Anxa1 or Hmgb1 in MCA205 and TC1 cell abolished the tumor-growth reducing effect of the combination therapy with CDDP plus (R)-crizotinib." (PMID 30940805, 2019). "However, another study showed that AnxA1 initiated autocrine signaling in breast cancer via FPR1 and led to an increase in tumor growth and metastasis." (PMID 31336833, 2019). "We suggest that along with the tumour cell secreted paracrine factors, ANXA1 diminishes proliferation and does not alter the cellular cytotoxicity." (PMID 30984541, 2019).
tumor (continued). "Interestingly, ANXA1 expression levels change significantly across the TCGA transcriptional GBM subtypes with mesenchymal and classical tumours displaying the highest levels and proneural tumours (frequently IDH1mutated) the lowest." (PMID 27770278, 2017). "Due to the fact that only CALD1 showed significant association with the type of response, while ANXA1 displayed only borderline significance, combination of ANXA1 and CALD1 stainings was not performed using tumor response as the endpoint of tamoxifen therapy." (PMID 26657294, 2016). "Particularly, we found a greater proliferation rate of ANXA1 KO MIA PaCa-2, a typical feature of more differentiated tumours, which could be, in this way, more easily attacked by chemotherapic agents." (PMID 27412958, 2016). "In accordance with our previous results, ANXA1 KO did not affect primary tumour growth, but significantly reduced the number of metastasis, above all those on the livers, which represent the first organs affected by PC metastatization." (PMID 27412958, 2016). "Despite the identification of ANXA1 as one of the several proteins that is differentially expressed during the progression of tumours to more malignant states, a functional role for ANXA1 in PC advancing is lacking." (PMID 25510623, 2014). "Co-localization of ANXA1/FPR2 was detected in the mast cells, neutrophils, and tumor cells." (PMID 25490767, 2014). "Taken together, our data suggested that the cross-talk between ANXA1 and COX-2 might play a critical role in cell proliferation and tumor growth." (PMID 25038797, 2014). "In primary tumors, non-invasive tumors or low ANXA1 expressing tumors (such as MCF7), ANXA1 may play a tumor suppressive role by keeping NF-κB activity in check via miR26b* regulation." (PMID 25536365, 2014). "Combined expression of SRC kinase, ANXA1, CAV-1 and EphA2 was found in 31 % of tumour samples." (PMID 25594008, 2014). "In the present study, we observed an increase in ANXA1 expression in HPV + cases compared to HPV- cases only in normal epithelium of the tumor margin." (PMID 24782913, 2014). "Immunostaining of ANXA1 was mostly weak or negative in the cytoplasm of cells from tumor margins (control group) compared to the samples from the HPV-negative (p<0.01, Tukey’s post hoc test) and HPV-high-risk (p<0.0001, Tukey’s post hoc test) groups." (PMID 23341933, 2013). "The expression of ANXA1 has been studied in various types of cancer, but there is no consensus concerning the role this protein plays during tumor initiation and/or progression." (PMID 23341933, 2013). "In this system, only the stroma in the tumor differs because the non-tumor cells are from the host body with or without annexin A1." (PMID 23077482, 2012). "These molecules showed most significant changes, either most down-regulated (log2 (ko/wt)<−0.999), or most up-regulated (log2 (ko/wt)>0.956), in the tumor stroma that lacked annexin A1." (PMID 23077482, 2012). "In the annexin A1 null animal model, these non-tumor cells infiltrated into tumor stroma do not express annexin A1, this lack of annexin A1 protein function reflected as the gene expression level changes of several other proteins." (PMID 23077482, 2012). "Through systems biology analysis, we found this list of genes that significantly changed in the tumor stroma that lacked annexin A1." (PMID 23077482, 2012). "Altogether, we conclude that ANXA1 is expressed in SCLC and its presence correlates with stromality and immune infiltrates, especially concerning the numbers of TAMs, where the protein expression of the molecule has been verified in situ apart from tumor cells in the TME." (PMID 40361334, 2025). "ANXA1 binds to macrophages’ FPR2, promoting TAMs polarization towards the immunosuppressive M2 phenotype in TME, by activating the PI3K/AKT and ERK1/2 pathways, leading to tumor progression stimulation by increasing cancer cell resistance to immune-mediated therapies." (PMID 41283264, 2025).
tumor (continued). "n = 5 patients showed no signs of ANXA1 protein expression either in tumor or in stromal cells." (PMID 40361334, 2025). "ANXA1 was uniquely expressed in PDAC tumor cells, unlike other cancers (as described later)." (PMID 41228323, 2025). "We performed a Spearman correlation analysis and pairwise comparison to reveal any connections between the diagnosis age, TMB, tumor stage, gender, and ANXA1 tumor expression, where none of the clinical parameters showed significant associations with the latter." (PMID 40361334, 2025). "Furthermore, we found two more patients with ANXA1 expression only in the stroma and on non-tumoral cells inside tumor nests." (PMID 40361334, 2025). "The lack of differences in expression between tumor and control samples for ANXA1 may be due to tissue lysates being a mixture of different cells." (PMID 38893148, 2024). "Moreover, AnxA1, known to regulate the nuclear localization of EGFR, promotes T cell dysfunction by favoring the EGFR/STAT3 transcriptional activities in cancer cells, enhancing immune evasion and tumor progression." (PMID 38645221, 2024). "ATP and ANXA1 ligate purinergic receptors of the purinergic receptor P2X 7 (P2RX7) type and formyl peptide receptor 1 (FPR1), respectively, thus facilitating the chemoattraction and homing of migratory cDC1s into the tumor bed, into the proximity of stressed and dying cancer cells." (PMID 37907944, 2023). "We did not detect Annexin A1 in culture supernatants of untreated, live tumour cells." (PMID 36123610, 2022). "Therefore, genes VEGFA, ANXA1, HSP90B1, PSMA7, PRDX6, and PPP1CB may be new targets for anti-tumor effects in the future." (PMID 36741702, 2022). "Finally, although tumor growth was reduced by knockdown of ANXA1, it did not decrease to a marginal level." (PMID 34991599, 2022). "The proportion of tumor-infiltrating immune cells, calculated by CIBERSORT algorithm, had a significant difference in distribution among the high and low ANXA1 expression groups, indicating that ANXA1 could be an important immune marker of TME." (PMID 34422796, 2021). "Importantly, HER-2+ (non-luminal) tumours depicted higher ANXA1 expression, which is consistent with previous studies that reported ANXA1 significance in hormone receptor (HR) negative BrC subtypes." (PMID 33276477, 2020). "However, until now a systematic study of anxA1 expression in tumor and normal vasculature has not been published." (PMID 32497150, 2020). "Thus, we proposed that ANXA1 contributes to the resolution of inflammation from non-tumor cells but otherwise exerts opposite effects in tumor cells." (PMID 29662435, 2018). "Some of these proteins are key components of cell-cell or cell-matrix adhesion and includes annexin and integrins such as ANXA1, ANAX2, ITGB1, ITGA3, FN1, CTNNB1, APOH which interplay may activate exosome and leukocyte adhesion to tumor cells to limit tumor growth." (PMID 30111323, 2018). "However, our data suggest that, in non-neoplastic epithelium, ANXA1 expression is increased in individuals whose tumor is positive for HPV." (PMID 24782913, 2014). "As the mechanism of ANXA1 in cancer progression has not been still completely clarified, more studies are required to investigate the detailed action mechanisms of this protein in tumours." (PMID 25510623, 2014). "A reduction in ANXA1 expression has been found in prostate cancer compared to non-tumor tissue." (PMID 24782913, 2014). "Using systems analysis programs commercially available, this paper further compared the gene expression between tumors from annexin A1 wild type mice and annexin A1 knockout mice and found a list of genes that significantly changed in the tumor stroma that lacked annexin A1." (PMID 23077482, 2012).